LGALS3 (galectin 3)
Diseases named in the same sentence as LGALS3 in open-access papers (continued):
Sharing a sentence is not in itself a finding about the gene and the disease.
fibrosis (80 papers, 2013 to 2025). the formation of excess fibrous connective tissue in an organ or tissue in a reparative or reactive process. "Galectin-3 (Gal-3) has emerged as a potential biomarker for risk stratification in chronic heart failure (HF), given its role in cardiac fibrosis and inflammation." (PMID 40734851, 2025). "Galectin-3 (Gal-3), a protein associated with cardiovascular fibrosis, has been identified as a potential therapeutic target in cardiac remodeling." (PMID 39767753, 2024). "Notably, some C15 genes were previously implicated in PH supporting the accuracy of our predictions; for example, inhibition of ABCC4 improved PH in mice and identification of LGALS3 (galectin-3) as a pathogenic factor in PH and right ventricular fibrosis." (PMID 34669463, 2021). "Among these, galectin-3 (gal-3) has emerged as a crucial biomarker due to its role in cardiac fibrosis, inflammation, and ventricular remodeling." (PMID 40747108, 2025). "Galectin-3 (Gal-3) has emerged as a significant biomarker in cardiac pathology due to its involvement in cardiac fibrosis, inflammation, and remodeling processes." (PMID 40842927, 2025). "As an established fibroinflammatory mediator, galectin-3 promotes cardiac fibrosis through multiple mechanisms, thus providing a substrate for the development and maintenance of potentially fatal arrhythmias." (PMID 39338248, 2024). "Previously published papers showed a direct link between galectin-3 and cardiac fibrosis and cardiac remodeling." (PMID 38535084, 2024). "So far, LGALS3 has been explored as a target by a number of teams and companies for diseases such as heart disease, fibrosis, and AD where a few drug compounds have made it to the phase II and III clinical trials." (PMID 39080267, 2024). "Galectin-3 induces pathologic remodelling of the heart, and is a culprit in the development of cardiac fibrosis in HF and electrical remodelling in atrial fibrillation." (PMID 37081960, 2023). "Galectin-3 (Gal-3) is an important factor in the pathophysiology of HF, mainly due to its role in cardiac fibrosis, inflammation, and ventricular remodeling." (PMID 37685918, 2023). "Further, on day 28 of life we observed cardiac fibrosis by Sirius Red staining, which was accompanied by an increase in mRNA expression of galectin-3 and CCL2 (chemokine (C-C motif) ligand 2) in whole hearts of hyperoxic pups, which improved with IL-1Ra." (PMID 31354700, 2019). "Collectively, these studies underscore the critical role of galectin-3 in mediating cardiac fibrosis and diastolic dysfunction, highlighting its potential as a therapeutic target for managing HFpEF and other cardiac conditions characterized by impaired diastolic function." (PMID 39063659, 2024). "Furthermore, the prospect of targeting galectin-3 presents a novel therapeutic strategy for cardiovascular diseases by mitigating cardiac fibrosis, hypertrophy, and inflammation." (PMID 39063659, 2024). "Furthermore, galectin-3 plays a relevant role in the formation of (liver) fibrosis, and specific galectin-3 inhibitors have been developed to target this process." (PMID 38332916, 2023). "Additionally, there was a significant increase in the expression of galectin-3 (Gals3), a marker of cardiac fibrosis and inflammation in various CVDs, in simGCRsim-IR mice (p < 0.05)." (PMID 38054039, 2023). "Galectin-3 is involved in cardiac fibrosis and remodeling, and our finding may have some bearing on the presence of diastolic dysfunction, known to be more prevalent in women than in men." (PMID 33831096, 2021). "Similarly, for cardiac phenotypes, we identified multiple genes related to cardiac fibrosis that were up-regulated in FRDAkd mice heart, including Lgals3, Icam1 and Timp1." (PMID 29257745, 2017). "Moreover, inhibition of galectin-3 holds promise in attenuating cardiac fibrosis and remodeling." (PMID 39063659, 2024). "Furthermore, miR-335-5p could also regulate angiotensin II-induced cardiac fibrosis and hypertrophy by targeting galectin-3." (PMID 36246958, 2022).
fibrosis (continued). "The usability of Galectin-3 and ST2 as appropriate predictive and prognostic biomarkers for the disease development or presence of fibrosis in canine DMVD should be further investigated." (PMID 35780161, 2022). "We reported that 12 serum markers of ECM metabolism, such as markers of collagen synthesis and controlling factors, including galectin-3, as well as the MMPs/TIMPs system, were of zero utility when it came to the prediction of EBM-assessed fibrosis in DCM." (PMID 34071085, 2021). "While some studies provide evidence of its vital role in fibrosis and dysfunction of the remodelling heart other investigations using galectin-3 knockout mice demonstrated that this is not a critical modulator of cardiac fibrosis but may be able to delay the hypertrophic response." (PMID 36968272, 2023).
Stroke (79 papers, 2011 to 2026). Sudden impairment of blood flow to a part of the brain due to occlusion or rupture of an artery to the brain. "Both galectin-3 and procalcitonin are reported to be associated with stroke severity and poor outcomes." (PMID 40863995, 2025). "A higher concentration of galectin-3 is associated with higher stroke severity and poor prognosis.It was thought to result from the upregulation response of galectin-3 to hypoxia-ischemic of the brain." (PMID 38892886, 2024). "Previous studies have demonstrated increased levels of galectin-3 in females; however, this observation was made in a population at risk for stroke." (PMID 38539500, 2024). "In another study, higher levels of serum galectin-3 were independently associated with an increased risk of death or major disability after stroke onset." (PMID 36873388, 2023). "Elevated blood galectin-3 levels were associated with prognostic outcomes after stroke, including functional outcome mRS and mortality rate." (PMID 36846691, 2023). "Another study also reports that stroke-associated microglia will up-regulate Spp1, Lgals3, and Cstb." (PMID 38067435, 2023). "Higher serum galectin-3 level was associated with mRS (OR [95% CI]: 2.02 [1.08, 3.77]) and mortality (OR [95% CI]: 2.17 [1.17, 4.02]) after stroke." (PMID 36846691, 2023). "The Pearson correlation analysis shows that baseline serum galectin-3 levels are negatively linked to cognitive function 3 months after the onset of stroke (r = −0.396, p < 0.05)." (PMID 34900086, 2021). "The results suggest that QSYQ exerts a neuroprotective role in the damaged brain caused by experimental stroke probably through modulating the galectin-3-mediated inflammatory response." (PMID 33953667, 2021). "The authors of another paper have stressed that higher galectin-3 serum concentrations determined in patients on admission to hospital are associated with severe course of stroke and frequently with a poor prognosis at discharge from hospital." (PMID 35053194, 2021). "Logistic regression analysis was used to analyze the association of serum galectin-3 with stroke prognosis at discharge." (PMID 33686023, 2021). "This study shows that higher serum levels of galectin-3 are associated with stroke severity at admission and stroke prognosis at discharge in ischemic stroke." (PMID 33686023, 2021). "Galectin-3 level had a strong association with poor stroke prognosis and unadjusted and adjusted risk increased 25% (OR, 1.25; 95%CI, 1.17-1.33; P<0.001) and 14% (OR, 1.14; 95%CI, 1.07-1.22; P<0.001), respectively for per unit(ng/ml) level increasing." (PMID 33686023, 2021). "In this prospective study, the data shows that higher serum levels of galectin-3 are associated with stroke severity at admission and stroke prognosis at discharge in ischemic stroke." (PMID 33686023, 2021). "Activated galectin-3 possibly causes the development of brain injury including neuroinflammation after stroke." (PMID 33552066, 2020). "It was shown that increased plasma levels of galectin-3 were associated with occurrence of postoperative strokes among female patients who undergo carotid endarterectomy." (PMID 29587379, 2018). "The aim of this study was to assess the expression patterns of serum galectin-1 (Gal-1), galectin-3 (Gal-3), galectin-9 (Gal-9), and galectin-3 binding protein (Gal-3BP) and their associations with stroke outcome in large artery atherosclerotic (LAA) stroke." (PMID 28112232, 2017). "Combined we show that stroke (pMCAO) triggers central and peripheral galectin-3 release causing enteric neuronal loss through a TLR4 mediated mechanism involving TAK1 and AMPK." (PMID 27612206, 2016). "Additionally, galectin-3 is implicated in several neuroinflammatory and neurodegenerative processes including multiple sclerosis, Alzheimer’s disease, and stroke, highlighting its potential role as a biomarker for neuroprognostication." (PMID 39338248, 2024). "High galectin-3 concentration is associated with an increased risk of stroke." (PMID 36846691, 2023).
Stroke (continued). "Besides that, higher levels of serum galectin-3 were independently correlated with increased risk of death, significant disability, recurrent stroke and vascular events." (PMID 35053194, 2021). "In addition, a combination of low HDL and high galectin-3 was found to be associated with poor prognosis after ischemic stroke, which includes the composite outcomes of death and vascular events, recurrent stroke, and vascular events." (PMID 34912287, 2021). "Moreover, we observed cumulative effects of sTREM2 and galectin-3 on stroke outcomes, patients with simultaneous elevations of sTREM2 and galectin-3 levels had substantially increased risk of death, cardiovascular events, as well as the composite outcome of death and severe disability." (PMID 35414082, 2022). "Our findings indicate that the upregulation of Ptgs2, Lgals3, Il6r, and Jak3 further enhances the inflammatory response following stroke." (PMID 39847586, 2025). "In the present work, we aimed to delineate the effects of mono- and combinatorial pre-treatment upon neurological status and neurological integrity biomarkers, namely protein S100b, GFAP, procalcitonin, and galectin-3, following a cerebrovascular accident." (PMID 40863995, 2025). "In this study, we aimed to delineate the effects of mono- and combinatorial pre-treatment upon neurological status and biomarkers, namely protein S100b, GFAP, procalcitonin, and galectin-3, following stroke." (PMID 40863995, 2025). "Other MG markers, such as Lgals3, Ifitm3 and Lgals3bp, were also upregulated in MG and other cells following stroke." (PMID 36824976, 2023). "The top five genes that were significantly upregulated in MG in the aged stroke brain included MG related genes (Lgals3, Lyz2, Lgals3bp) and another interferon-stimulated gene (ISG), Ifitm3." (PMID 36824976, 2023). "The outcomes included the modified Rankin Scale (mRS), mortality rate, and prognostic accuracy of galectin-3 on mRS after stroke." (PMID 36846691, 2023). "Data from eligible studies on the relationship between galectin-3 and stroke prognosis were extracted for the meta-analysis." (PMID 36846691, 2023). "Galectin-3 supports neuro-vascular protection and functional post-stroke recovery by modulating angiogenic and apoptotic pathways in the brain." (PMID 36873388, 2023). "Galectin-3, a microglia/macrophage-derived inflammatory mediator, plays a role in the stroke progression." (PMID 33686023, 2021). "The data suggested that the beneficial effects of QSYQ on brain damage and neurological behavioral dysfunction induced by experimental stroke were partly via the modulation of galectin-3-mediated inflammatory reaction." (PMID 33953667, 2021). "More research needs to be performed in the future to test the relationship between the galectin-3 and stroke prognosis." (PMID 33686023, 2021). "The level of galectin-3 was significantly higher in the vehicle-treated stroke rats compared with the sham-operated rats." (PMID 34122007, 2021). "Univariate and multivariate logistic analysis was used to analyze serum galectin-3 with moderate-to-high stroke severity at admission." (PMID 33686023, 2021). "The multivariable model included demographic characteristics, clinical findings at admission, vascular risk factors, NIHSS at admission, stroke subtype, acute stroke treatment, and serum levels of CRP, FSG, and galectin-3." (PMID 33686023, 2021). "A recent research report showed that high serum galectin-3 levels can predict the severity of stroke at admittance and the prognosis of stroke at discharge in ischemic stroke patients." (PMID 34900086, 2021). "In response to cerebral damage induced by stroke, high level expression of galectin-3 was observed in activated microglial cells localized in the ischemic lesion." (PMID 33953667, 2021). "The protein expression level of galectin-3 was significantly increased in brain tissues of stroke rats in the subacute phase compared with the sham group." (PMID 33953667, 2021).
Stroke (continued). "Accumulating evidence suggests that many types of MCPs, such as TNC, periostin, galectin-3, and osteopontin, contribute to aggravation or improvement of neuroinflammation in stroke at least partly by influencing the expression of each other." (PMID 33552066, 2020). "An experimental study of ischemic stroke found that galectin-3 is overexpressed in activated microglial cells and is involved in the inflammatory response in stroke." (PMID 31888302, 2019). "We investigated possible consequences of stroke on the enteric nervous system and the involvement of galectin-3." (PMID 27612206, 2016). "Neuroimmune interactions involving galectin-3, released from microglia in the brain, mediates the post-stroke pro-inflammatory response." (PMID 27612206, 2016). "High galectin-3 was a significant independent predictor of the composite of all-cause mortality, non-fatal MI, and stroke (adjusted hazard ratio 1.670, 95% confidence interval 1.014–2.751, p = 0.044)." (PMID 40747494, 2025). "In the high galectin-3 group, the composite of all-cause mortality, non-fatal MI, and stroke occurred in a total of 65 patients (13.8%), while in the low galectin-3 group, they occurred only in 27 patients (5.8%) during long-term follow-up." (PMID 40747494, 2025). "Association between galectin-3 and composite of all-cause mortality, non-fatal MI, and stroke according to the presentation of ACS." (PMID 40747494, 2025). "The high galectin-3 group had a significantly higher incidence of all-cause mortality, cardiac mortality, and composite of all-cause mortality, non-fatal MI, and stroke." (PMID 40747494, 2025). "Future studies to lower the galectin-3 level may provide a new direction to reduce disease severity and improve the prognosis of stroke." (PMID 36846691, 2023). "Galectin-3 had a good predictive ability on mRS after stroke (AUC: 0.88, 95% CI:0.85, 0.91)." (PMID 36846691, 2023). "The CH25H+ microglia (MG6) express several neurotrophic factors, including Spp1, Gpnmb, and Lgals3, which was previously suggested to induce axon outgrowth and establish functional synapses, thus may contribute to neurogenesis after stroke." (PMID 37183260, 2023). "This study investigated the relationship between blood galectin-3 levels and stroke prognosis." (PMID 36846691, 2023). "Second, the causality conclusion could not be confirmed in this study, and whether lowering blood concentration of galectin-3 could improve the prognosis of stroke patients requires further research." (PMID 33686023, 2021). "Second, our data demonstrated that post-stroke VPA treatment could suppress the upregulation of galectin-3, which is required for resident microglia activation in response to ischemic injury." (PMID 34122007, 2021). "In recent years, galectin 3 has become an emerging biomarker of stroke and cerebrovascular disease." (PMID 34900086, 2021). "In multivariate analysis, galectin-3 remained a high stroke severity predictor with an adjusted OR of 1.16 (95% CI, 1.08–1.22; P<0.001), after adjusted for demographic characteristics, clinical findings at admission, vascular risk factors, stroke subtype, and serum levels of CRP and FSG." (PMID 33686023, 2021). "Combining the results of this study it can be assumed that the release of Galectin-3 following stroke may induce enteric neuronal cell death via TLR4 activation involving TAK1 and AMPK." (PMID 32455781, 2020). "Measuring stroke area four days after induction of ischemia and 72 h after the application of recombinant Galectin-3 showed significant reduction in the size of ischemic lesions in mice receiving recombinant Galectin-3 compared to control." (PMID 32455781, 2020). "TNC directly binds to other MCPs periostin and galectin-3, and may regulate the expression levels of each other in stroke, playing diverse roles." (PMID 33552066, 2020). "Galectin-3 is suggested a target for treatment of post-stroke complications." (PMID 27612206, 2016).